DMRTC1 (DMRT like family C1)
Synonyms: DMRT8
Gene: Protein-coding gene on chromosome X (72,872,025 to 72,943,837, reverse strand). Ensembl gene ENSG00000269502.
Subcellular location (Human Protein Atlas): Nucleoplasm; Intermediate filaments
Gene Ontology:
Molecular function: DNA-binding transcription factor activity, RNA polymerase II-specific; RNA polymerase II cis-regulatory region sequence-specific DNA binding
Biological process: regulation of DNA-templated transcription
Cellular component: chromatin; nucleus
Homologues: Orthologues: chimpanzee DMRTC1B (100% identical), macaque DMRTC1B (97% identical), Caenorhabditis elegans dmd-7 (16% identical), Caenorhabditis elegans dmd-4 (14% identical), Drosophila melanogaster dmrt99B (13% identical), Caenorhabditis elegans dmd-9 (10% identical), Caenorhabditis elegans dmd-5 (8% identical). Paralogues in human: DMRTC1B (100% identical), DMRTC2 (51% identical), DMRTA1 (21% identical), DMRTA2 (21% identical), DMRT3 (20% identical), DMRT2 (15% identical), DMRT1 (15% identical), DMRTB1 (11% identical).